PPP5C (protein phosphatase 5 catalytic subunit)
Description:
Serine/threonine-protein phosphatase that dephosphorylates a myriad of proteins involved in different signaling pathways including the kinases CSNK1E, ASK1/MAP3K5, PRKDC and RAF1, the nuclear receptors NR3C1, PPARG, ESR1 and ESR2, SMAD proteins and TAU/MAPT. Implicated in wide ranging cellular processes, including apoptosis, differentiation, DNA damage response, cell survival, regulation of ion channels or circadian rhythms, in response to steroid and thyroid hormones, calcium, fatty acids, TGF-beta as well as oxidative and genotoxic stresses. Participates in the control of DNA damage response mechanisms such as checkpoint activation and DNA damage repair through, for instance, the regulation ATM/ATR-signaling and dephosphorylation of PRKDC and TP53BP1. Inhibits ASK1/MAP3K5-mediated apoptosis induced by oxidative stress. Plays a positive role in adipogenesis, mainly through the dephosphorylation and activation of PPARG transactivation function (By similarity). Also dephosphorylates and inhibits the anti-adipogenic effect of NR3C1 (By similarity). Regulates the circadian rhythms, through the dephosphorylation and activation of CSNK1E. May modulate TGF-beta signaling pathway by the regulation of SMAD3 phosphorylation and protein expression levels. Dephosphorylates and may play a role in the regulation of TAU/MAPT. Through their dephosphorylation, may play a role in the regulation of ions channels such as KCNH2 (By similarity). Dephosphorylate FNIP1, disrupting interaction with HSP90AA1/Hsp90.
Synonyms: PP5; PPT; PPP5
Tractability: Small molecule: a drug acting on it is in phase 2 or 3 trials; a structure with a bound ligand is known; a high-quality ligand is known; it has a high-quality binding pocket; it belongs to a druggable protein family. Antibody: UniProt places it where antibodies can reach, with high confidence; its Gene Ontology location is reachable by antibodies, with medium confidence. PROTAC: ubiquitination databases record sites on it; its protein half-life has been measured; a small molecule that binds it is known.
Target class: Protein Phosphatase; Phosphatase; Serine/threonine protein phosphatase; Enzyme
Gene: Protein-coding gene on chromosome 19 (46,347,003 to 46,392,981, forward strand). Ensembl gene ENSG00000011485.
Subcellular location: Nucleus; Cytoplasm; Cell membrane
Subcellular location (Human Protein Atlas): Cytosol; Vesicles
Pathways (Reactome):
Signal Transduction: ESR-mediated signaling; Negative regulation of MAPK pathway
DNA Repair: Recruitment and ATM-mediated phosphorylation of repair and signaling proteins at DNA double strand breaks
Gene Ontology:
Molecular function: ADP binding; ATP binding; Hsp90 protein binding; identical protein binding; phosphatase activity; protein binding; protein serine/threonine phosphatase activity; phosphoprotein phosphatase activity; tau protein binding; G-protein alpha-subunit binding; heat shock protein binding; Hsp70 protein binding; hydrolase activity; microtubule binding; mitogen-activated protein kinase kinase kinase binding; protein serine/threonine kinase inhibitor activity; protein-containing complex binding; RNA binding
Biological process: peptidyl-serine dephosphorylation; positive regulation of canonical NF-kappaB signal transduction; DNA-templated transcription; double-strand break repair; MAPK cascade; mitotic cell cycle; response to arachidonate; response to lead ion; cellular response to cadmium ion; cellular response to hydrogen peroxide; negative regulation of apoptotic process; negative regulation of MAPK cascade; positive regulation of nuclear receptor-mediated glucocorticoid signaling pathway
Cellular component: cytoplasm; cytosol; nucleus; plasma membrane; protein folding chaperone complex; protein-containing complex; nucleoplasm; neuronal cell body; perikaryon; proximal dendrite
Genetic constraint (gnomAD): Loss-of-function variants: 21 observed, 66.28 expected, observed/expected ratio (o/e) 0.32, 90% interval 0.22 to 0.46. The upper end of that interval is the gene's LOEUF score, 0.46, which puts it in group 2 of 6, group 1 being the genes least tolerant of losing a copy. Missense variants: 464 observed, 678.21 expected, observed/expected ratio (o/e) 0.68, 90% interval 0.63 to 0.74. Synonymous variants: 246 observed, 256.74 expected, observed/expected ratio (o/e) 0.96, 90% interval 0.86 to 1.07.
Homologues: Orthologues: dog PPP5C (98% identical), guinea pig PPP5C (98% identical), rat Ppp5c (98% identical), mouse Ppp5c (98% identical), pig PPP5C (97% identical), chimpanzee PPP5C (97% identical), macaque PPP5C (96% identical), zebrafish ppp5c (81% identical), tropical clawed frog ppp5c (77% identical), rabbit PPP5C (73% identical), Drosophila melanogaster PpD3 (60% identical), Caenorhabditis elegans pph-5 (57% identical). Paralogues in human: PPEF2 (31% identical), PPEF1 (28% identical), PPP3CB (24% identical), PPP3CC (23% identical), PPP3CA (23% identical), PPP6C (23% identical), PPP1CC (22% identical), PPP4C (22% identical), PPP1CA (22% identical), PPP1CB (22% identical), PPP2CA (22% identical), PPP2CB (22% identical).
Diseases named in the same sentence as PPP5C in open-access papers:
PPP5C is named in the same sentence as 32 diseases in open-access papers, as found by Europe PMC text mining. Sharing a sentence is not in itself a finding about the gene and the disease. The quoted sentences say what the papers report.
pancreatic cancer (4 papers, 2021 to 2023). "Among all the PPPcs, PPP1CB, PPP1CC, PPP2CA, PPP2CB, PPP3CB, and PPP5C had tight associations with at least one of the pancreatic cancer related genes in that list." (PMID 33270085, 2021). "The miR-520a-5p plays an essential role in regulating gemcitabine resistance by directly targeting PPP5C in pancreatic cancer." (PMID 36829181, 2023). "In conclusion, this study explored the role of PPP5C in pancreatic cancer by combining bioinformatics analysis and experiments and found the target relationship between miR-520-5p and PPP5C." (PMID 35957917, 2022). "The role of PPP5C in pancreatic cancer is similar to that in other cancers: it leads to the progression of pancreatic cancer by enabling tumors to develop resistance to gemcitabine." (PMID 35957917, 2022). "From these results, we can conclude that miR-520a-5p can inhibit the growth of pancreatic cancer by targeting PPP5C inhibition." (PMID 35957917, 2022). "And since the occurrence of PPP5C is closely related to the abnormal activation of tumor driver genes, the exploration of pancreatic cancer-related genes has been of increasing interest to researchers in recent years." (PMID 35957917, 2022). "At the same time, compared with previous studies on PPP5C and pancreatic cancer, this study examined the expression of miR-520a-5p in pancreatic cancer and its relationship with PPP5C." (PMID 35957917, 2022). "Combined with our results on autophagy, we can conclude that PPP5C can promote the metastasis of pancreatic cancer cells." (PMID 35957917, 2022). "PPP5C has a prognostic role in pancreatic cancer by promoting the value-added and invasion of pancreatic cancer cells, and a targeted inhibitory relationship between miR-520-5p and PPP5C was found." (PMID 35957917, 2022). "In this connection, our study effectively proves that the role of PPP5C in pancreatic cancer is similar to that in other cancers." (PMID 35957917, 2022). "So, how to study the role played by PPP5C in pancreatic cancer?" (PMID 35957917, 2022). "However, the role of this type of miRNA in pancreatic cancer, as well as its relationship with PPP5C, has been less well-studied." (PMID 35957917, 2022). "Therefore, targeting the inhibition of PPP5C is particularly important in the treatment of pancreatic cancer, while miRNAs regulate the properties of mRNA expression by binding to its 3’-UTR." (PMID 35957917, 2022). "Results of the present study suggest that PPP1CA, PPP1CB, PPP2CA, PPP2CB, and PPP3CA have deleterious effects but PPP3CB, PPP5C, and PPP6C have beneficial effects on pancreatic cancer." (PMID 33270085, 2021). "In recent years, it has been reported that PPP1CA, PPP1CB, PPP2CA, PPP2CB, and PPP3CA accelerate the progression of pancreatic cancer, while PPP3CB, PPP5C, and PPP6C hinder PAAD progression." (PMID 34125004, 2021). "In contrast, patients with pancreatic cancer and high transcription levels of PPP3CB, PPP5C, PPP6C, and PPEF2 seemed to have better prognosis." (PMID 33270085, 2021).
breast carcinoma (2 papers, 2021 to 2022). "Except for PPP1CB, PPP1CC, PPP5C and PPEF1, the mRNA expression levels of the PPPCs family in breast cancer tissues were significantly different from those in paracancerous tissues." (PMID 34964699, 2022). "PPP1CC, PPP5C and PPEF2 were not aberrantly expressed in breast cancer tissues." (PMID 34964699, 2022).
prostate carcinoma (2 papers, 2021 to 2023). A carcinoma that arises from epithelial cells of the prostate gland. "By searching the members of the protein serine/threonine phosphatase family, we found PPP5C could significantly promote the tumor cell proliferation and survival, including HCC, ovarian cancer and prostate cancer." (PMID 34587164, 2021).
Alzheimer disease (1 paper, 2024). A progressive, neurodegenerative disease characterized by loss of function and death of nerve cells in several areas of the brain leading to loss of cognitive function such as memory and language. "Dysregulation or abnormal activity of PPP5C is implicated in various diseases, including several cancers, obesity, and Alzheimer’s disease." (PMID 38302916, 2024).
developmental and epileptic encephalopathy (1 paper, 2025). An epilepsy associated with developmental impairment that may be due to either the underlying etiology or the superimposed epileptic activity, or both. "New findings indicate a potential association between the PPP5C (protein phosphatase 5 catalytic subunit) gene (OMIM# 600658) and developmental and epileptic encephalopathy (DEE, OMIM#308350)." (PMID 40172746, 2025). "Emerging evidence suggesting a possible link between the PPP5C gene (protein phosphatase 5 catalytic subunit; OMIM#600658) and developmental and epileptic encephalopathy (DEE, OMIM#308350), although the clinical significance of pathogenic variants in this gene remains unclear." (PMID 40172746, 2025).
developmental delays (1 paper, 2025). "Interestingly, a recent discovery report of a de novo missense variant in PPP5C in an eight-year-old girl with microcephaly, epilepsy, and developmental delays suggests a potential role for this gene in DEE." (PMID 40172746, 2025).
epilepsy (1 paper, 2025). A brain disorder characterized by episodes of abnormally increased neuronal discharge resulting in transient episodes of sensory or motor neurological dysfunction, or psychic dysfunction. "Thus, the potential role of pathogenic variants in the PPP5C gene in epilepsy and neurodevelopmental disorders warrants significant attention." (PMID 40172746, 2025).
Intellectual disability (1 paper, 2021). "Although the de novo stop-gain variant of MED13L p.Arg1760∗ was previously reported in an intellectual disability case, we also identified de novo variants of PPP5C and NCKAP1L in the same individual with the MED13L variant." (PMID 33748132, 2021).
ischemic stroke (1 paper, 2025). A stroke disorder caused by obstruction of blood flow to the brain, due to thrombotic (local blood clot formation) or embolic (due to a blood clot or other material traveling from another site) event. "In ischemic stroke, we found that MPO, CALCRL, PPP5C, KTN1-AS1, CCR1, CTB-50L17.9, CCR9, ZNF362, ZIK1, ELP5, CKAP2, NUP88, and SEC16A show risk effects (OR > 1)." (PMID 40624693, 2025).
learning disabilities (1 paper, 2025). "Additionally, the patient was diagnosed with learning disorders at the age of 8, a condition not previously linked to PPP5C gene mutations." (PMID 40172746, 2025).
lung adenocarcinoma (1 paper, 2020). A carcinoma that arises from the lung and is characterized by the presence of malignant glandular epithelial cells. "Only NCOR2 and PPP5C met the following requirements: it is down-regulated by more than 1.5 times in A549/DDP, interacts with CHAF1B, has a ubiquitination site and is lowly expressed in lung adenocarcinoma." (PMID 32508530, 2020).
mouth ulcers (1 paper, 2019). "For example, rs7749390 an intronic variant in the IFNGR1 gene and rs3764613 within PPP5C, showed very strong evidence for associations with mouth ulcers (OR 1.08, 95% CI: 1.07, 1.08; EAF 0.61; P = 2.0e−62 and OR 0.93, 95% CI: 0.92, 0.93; EAF 0.43; P = 7.4e−73, respectively)." (PMID 30837455, 2019).
pancreatic adenocarcinoma (1 paper, 2021). "In this work, we found that the mRNA expression of PPP5C was higher in pancreatic adenocarcinoma than in normal tissues and that its level correlated with tumor stage." (PMID 33270085, 2021).
renal carcinoma (1 paper, 2022). A carcinoma arising from the epithelium of the renal parenchyma or the renal pelvis. "On the cancer side, the role of PPP5C in proliferation and cell survival and its unique structure make it a potentially attractive therapeutic target, and elevated PPP5C expression has been found to increase proliferation in most cells in breast and renal cancer clinical studies." (PMID 35957917, 2022).
cancer (6 papers, 2018 to 2025). A tumor composed of atypical neoplastic, often pleomorphic cells that invade other tissues. "Dysregulation of PPP5C has been linked to cancer progression and other disorders due to its critical role in cell cycle control and stress response regulation." (PMID 40172746, 2025). "This makes PPP5C a potential drug target in several diseases, including obesity, cancer, and Alzheimer’s disease." (PMID 40172746, 2025). "This will lead to the overexpression of PPP5C, which is one of the reasons for cell proliferation and the progression of various cancers." (PMID 35957917, 2022). "In contrast, PPP5C mentioned in this study is a cancer-promoting factor in many cancers." (PMID 35957917, 2022). "PPP5C plays a pivotal role in regulating cell growth, and studies have shown thatPPP5C knockdown could inhibit cancer cell proliferation." (PMID 33270085, 2021).
tumor (3 papers, 2021 to 2022). "Furthermore, our angiogenesis experiments suggest that PPP5C can promote further deterioration of the tumor." (PMID 35957917, 2022). "After analysis of the TCGA database, it was found that the higher the expression level of PPP5C among tumors, the worse the prognosis of tumor patients, and the ROC curve analysis revealed that PPP5C could be used more accurately to predict the survival rate of patients within 3-5 years." (PMID 35957917, 2022).
PPP5C also shares sentences with these, for which no sentence is quoted: autism (2 papers); ankylosing spondylitis (1); arthropathy (1); autism spectrum disorder (1); bacterial infection (1); behavioral disorders (1); Epileptic encephalopathy (1); microcephaly (1); neuroblastoma (1); neurodevelopmental disorder (1); non‐small cell lung cancer (1); Obesity (1); ovarian carcinoma (1); psoriasis (1); ulcerative colitis (1); varicocele (1).